WFS1 (wolframin ER transmembrane glycoprotein)
Diseases named in the same sentence as WFS1 in open-access papers (continued):
Sharing a sentence is not in itself a finding about the gene and the disease.
Wolfram syndrome (continued). "WFS1 variants are typically associated with and discussed as the drivers of Wolfram syndrome; however, WFS1 variants have additionally been identified as risk factors for the development of T2DM." (PMID 36613674, 2022). "Expression of WFS1 p.R558C was more stable compared with the other known recessive pathogenic variants associated with Wolfram syndrome." (PMID 36134655, 2022). "One study reported associations of heterozygous WFS1 mutations with mild form of Wolfram syndrome and type 2 diabetes in Ashkenazi Jewish individuals." (PMID 36208030, 2022). "The mitochondrial fusion and localization in the neurons of Wfs1 knockout mice are impaired, and about 70% of patients with Wolfram syndrome caused by WFS1 mutation have sensorineural hearing loss." (PMID 36278017, 2022). "Most cases of Wolfram syndrome are caused by pathogenic variants in the WFS1 gene, which encodes a transmembrane protein localized to the endoplasmic reticulum (ER)." (PMID 35399956, 2022). "Of the approximately 200 WFS1 variants associated with Wolfram syndrome, approximately 35% are missense, 25% are nonsense, 21% are frameshift, 13% are in-frame insertions or deletions, and 3% are splice-site variants." (PMID 36134655, 2022). "The majority of patients with Wolfram syndrome develop diabetes mellitus due to the pathogenic WFS1 variants causing detrimental effects in pancreatic β cells." (PMID 36134655, 2022). "They cause various conditions including neonatal diabetes, maturity-onset diabetes of the young (MODY), and diabetes-associated syndromes (e.g. Wolfram syndrome due to variants in WFS1, Wolcott–Rallison syndrome)." (PMID 35227307, 2022). "Wolfram syndrome 1, a rare autosomal recessive neurodegenerative disease, is caused by mutations in the WFS1 gene." (PMID 35206658, 2022). "Wolfram syndrome is a rare genetic disorder largely caused by pathogenic variants in the WFS1 gene and manifested by diabetes mellitus, optic nerve atrophy, and progressive neurodegeneration." (PMID 36134655, 2022). "Human induced pluripotent stem cell–derived (iPSC-derived) islets (SC-islets) homozygous for WFS1 c.1672C>T variant recapitulated genotype-related Wolfram syndrome phenotypes." (PMID 36134655, 2022). "In this section, we will describe the genetic basis for Wolfram syndrome, a well-recognized prototype of ER stress-related disease, and the relationship between its causative gene, WFS1 and T2DM risk." (PMID 36613674, 2022). "The diabetes stem cell field has recently leveraged this technology to correct the WFS1 pathogenic variant using CRISPR/Cas9 gene-edited SC-islets from a patient with Wolfram syndrome to reverse preexisting diabetes in a mouse." (PMID 36134655, 2022). "Wolfram syndrome has been recognized as a spectrum disorder since recessive WFS1 variants can vary in clinical severity." (PMID 36613674, 2022). "We previously reported on the restoration of Wolfram phenotypes by correcting pathogenic WFS1 variants with CRISPR/Cas9 in SC-islets derived from patients with typical Wolfram syndrome." (PMID 36134655, 2022). "In this study, we characterize a likely unique pathogenic WFS1 c.1672C>T, p.R558C variant, which is associated with a mild form of Wolfram syndrome and highly prevalent in the Ashkenazi Jewish population." (PMID 36134655, 2022). "Wolfram syndrome, an autosomal recessive disease caused by mutations in WFS1, is characterized by juvenile-onset diabetes." (PMID 33751396, 2022). "Using exome sequence data from individual V:3, candidate variants obtained from filtering as well as Wolfram syndrome genes WFS1 and CISD2 were evaluated via the Integrative Genomics Viewer (IGV)." (PMID 33879837, 2021). "In humans, low frequency hearing loss is rare and can be associated with non-syndromic deafness DFNA1, Wolfram Syndrome 1 (WFS1) and with Meniere’s Disease." (PMID 34597341, 2021).
Wolfram syndrome (continued). "In another study, the CRISPR-Cas9 system was used to correct a diabetes-causing pathogenic variant of the Wolfram syndrome 1 (WFS1) gene in iPSCs derived from a patient with Wolfram syndrome (WS)." (PMID 33996792, 2021). "Wolfram syndrome (WS) is a rare autosomal recessive disorder caused by mutations in the Wolframin 1 (WFS1) gene." (PMID 34831417, 2021). "The majority of Wolfram syndrome 1 patients have biallelic homozygous or compound heterozygous mutations in the WFS1 gene; however, autosomal dominant inherited or de novo mutations in the same gene have also been reported in some individuals." (PMID 34992533, 2021). "We then sought to determine which mutations found in our search were associated with Wolfram Syndrome patients and which mutations were associated with heterozygous carriers of WFS1 mutations." (PMID 34746052, 2021). "Patients with Wolfram syndrome caused by mutations in WFS1 suffer from early onset diabetes as well as optic atrophy, deafness, ataxia, and dementia." (PMID 34079523, 2021). "Herein, we show that ER to Golgi transfer of vesicular cargo proteins requires WFS1, an ER-associated membrane protein whose loss of function leads to Wolfram syndrome." (PMID 34848728, 2021). "Mutations in the WFS1 gene, encoding wolframin (WFS1), cause endoplasmic reticulum (ER) stress and are associated with a rare autosomal-recessive disorder known as Wolfram syndrome (WS)." (PMID 33693650, 2021). "Mutations in the gene WFS1, coding for the protein wolframin, cause Wolfram Syndrome and are associated with bipolar disorder and schizophrenia." (PMID 34746052, 2021). "Note that two mutations in wolframin (A559T and A684V) were present in both Wolfram Syndrome and heterozygous carriers of WFS1 mutations in multiple cases." (PMID 34746052, 2021). "A recent study showed that sodium valproate also reduces ER stress and cell apoptosis in Wolfram syndrome 1 models caused by dominant WFS1 mutations." (PMID 34992533, 2021). "Wolfram syndrome (WFS) is a rare autosomal recessive genetic disease whose main cause is mutations in the WFS1 and CISD2 genes." (PMID 34404380, 2021). "The WFS1 gene was identified as a major causative locus for Wolfram syndrome, which is a monogenic form of diabetes and neurodegeneration characterized by juvenile diabetes, optic atrophy, and deafness." (PMID 34848728, 2021). "Mutations in WFS1 are responsible for many different clinical presentations with dominant and recessive inheritance, including the Wolfram syndrome, autosomal recessive non-syndromic OA, isolated DOA, and DOA associated with hearing loss." (PMID 33841295, 2021). "Genetic variants in the WFS1 gene can cause Wolfram syndrome (WS) or autosomal dominant nonsyndromic low-frequency hearing loss (HL)." (PMID 34258273, 2021). "The WFS1 gene, encoding wolframin (WFS1), causes endoplasmic reticulum stress and is linked to a rare autosomal-recessive disorder known as Wolfram syndrome." (PMID 34869039, 2021). "Here, the authors identify the WFS1 protein, which is mutated in Wolfram syndrome and associated with diabetes, as an ER to Golgi cargo receptor required for normal insulin processing and secretion." (PMID 34848728, 2021). "Mutations in WFS1, causing Wolfram syndrome, lead to chronic endoplasmic reticulum stress activating the unfolded protein response, which impairs survival of β-cells and neurons." (PMID 34079523, 2021). "Wolfram syndrome, an autosomal recessive disease caused by mutations in WFS1, is characterized by juvenile diabetes." (PMID 34680532, 2021). "Wolfram syndrome is considered a monogenic disorder, however, behavioral traits associated with polymorphisms in the WFS1 gene are more complex." (PMID 32723293, 2020). "Genomic defect of the Wfs1 gene causes Wolfram syndrome through loss of human β-cells, supporting an importance of appropriate proteostasis in the β-cells." (PMID 33294783, 2020).
Wolfram syndrome (continued). "WFS1 was known as the main pathogenic gene of Wolfram syndrome, which is an autosomal recessive neurodegenerative disorder characterized by visual symptoms, diabetes mellitus, central diabetes insipidus, and deafness." (PMID 32148946, 2020). "Rare mutations in the human WFS1 gene, located on human chromosome 4, are responsible for the development of Wolfram syndrome, which is considered monogenic." (PMID 32723293, 2020). "Mutations of the WFS1 gene are responsible for most cases of Wolfram syndrome (WS), a rare, recessively inherited neurodegenerative disorder characterized by juvenile-onset non-autoimmune diabetes mellitus and optic atrophy." (PMID 31937257, 2020). "Mutations in WFS1, the wolframin gene, are responsible for the development of Wolfram syndrome, an autosomal recessive disease characterized by a variety of disorders including diabetes mellitus." (PMID 32961860, 2020). "The purpose of the present study was mutational analysis of the WFS1 gene and investigation of the genotype‐phenotype correlation in a consanguineous Iranian family with Wolfram's syndrome." (PMID 32419160, 2020). "A homozygous mutation in WFS1 was identified in three children; mutations in this gene cause Wolfram syndrome, a recessive disorder characterized by childhood‐onset diabetes mellitus, optic atrophy and deafness." (PMID 31276222, 2019). "Mutations in WFS1 (associated with Wolfram syndrome) accounted for 50% of the monogenic diabetes cases." (PMID 31276222, 2019). "Wfs1 mutations are responsible for the Wolfram syndrome, characterized by diabetic and neurological symptoms." (PMID 30930784, 2019). "Wolfram syndrome is a rare disease caused by mutations in the WFS1 gene leading to symptoms in early to mid-childhood." (PMID 30979932, 2019). "Wolfram syndrome gene (WFS1) has been indicated to play a role in the susceptibility for mood disorders." (PMID 31114610, 2019). "Wolfram syndrome is a rare multisystem disorder caused by mutations in WFS1 or CISD2 genes leading to brain structural abnormalities and neurological symptoms." (PMID 31796109, 2019). "We carefully evaluated the medical history of these 3 subjects for age, gender, specific WFS1 gene mutations, and the age of onset for the major clinical components of Wolfram syndrome." (PMID 30914711, 2019). "The pathogenesis of Wolfram syndrome is attributed to genetic mutations in two genetic loci on chromosome 4 (WFS1 and CISD2- also known as ZCD2 gene or WFS2 gene)." (PMID 31796109, 2019). "Wolfram syndrome a genetic condition of diabetes, optic atrophy neurodegeneration, and psychiatric illness, is reported to be caused by mutation of WFS1 gene." (PMID 32231775, 2019). "Wolfram syndrome is a rare autosomal recessive disorder that is caused by mutations in the WFS1 or, less commonly, the WFS2 gene." (PMID 31375124, 2019). "Two genetically distinct variants have been identified, type-1 and type-2 Wolfram syndrome, which result from mutations in the WFS1 and CISD2, respectively." (PMID 31796109, 2019). "Among three children with a mutation in WFS1, the extra‐pancreatic features associated with Wolfram syndrome were present in only one child." (PMID 31276222, 2019). "This case series also supports previous observations that variants in WFS1 can be associated with non-syndromic OA instead of Wolfram syndrome." (PMID 31765440, 2019). "Mutations causing Wolfram syndrome are spread over the entire coding region in WFS1, and are typically inactivating, suggesting that a loss of function causes the disease phenotype." (PMID 29529044, 2018). "Wolfram syndrome (WS) is a rare autosomal recessive disorder caused by mutations in the WFS1 (Wolframin1) gene." (PMID 29976929, 2018). "Wolfram syndrome (WS) is a rare neurodegenerative disorder caused by biallelic mutations of the Wolframin1 (WFS1) gene and whose main symptoms are diabetes mellitus, optic nerve atrophy, hearing loss, and neurodegeneration in the brainstem." (PMID 29976929, 2018).
Wolfram syndrome (continued). "Wolfram syndrome (WS), caused by loss-of-function mutations in the Wolfram syndrome 1 gene (WFS1), is characterized by juvenile-onset diabetes mellitus, bilateral optic atrophy, and a wide spectrum of neurological and psychiatric manifestations." (PMID 29357349, 2018). "Wolfram syndrome (WS), caused by mutations of the Wolfram syndrome 1 (WFS1) gene on chromosome 4p16.1, is an autosomal recessive disorder characterized by diabetes insipidus (DI), neuro-psychiatric disorders, hearing deficit, and urinary tract anomalies." (PMID 29549887, 2018). "Studying the possible relations between Wfs1 and dopamine receptors is thereforecrucial for understanding the etiology and pathophysiology of the psychiatricsymptoms of Wolfram syndrome patients carrying mutant alleles at this locus." (PMID 28267787, 2017). "Wolfram syndrome (WS) is a rare autosomal-recessive disorder that is caused by mutations in the WFS1 gene and is characterized by juvenile-onset diabetes, optic atrophy, hearing loss and a number of other complications." (PMID 28860598, 2017). "In humans, loss of functional WFS1 proteinresults in Wolfram syndrome, characterized by diabetes insipidus, diabetes mellitus,optic atrophy and progressive sensorineural deafness often accompanied bypsychiatric and neurological symptoms." (PMID 28267787, 2017). "Wolfram syndrome, an autosomal recessive disorder characterized by juvenile‐onset diabetes mellitus and optic atrophy, is caused by mutations in the WFS1 gene." (PMID 27053292, 2016). "Ex vivo magnetic resonance imaging of the brains of Wfs1-/- mice also demonstrated clear atrophy and/or degeneration of the brain stem, which is the main structure atrophied in Wolfram syndrome patients and the cause of death due to respiratory failure." (PMID 27434582, 2016). "The majority of Wolfram syndrome cases are caused by mutations in the gene Wolfram syndrome 1 (WFS1), which encodes for a protein localized to the endoplasmic reticulum (ER) membrane." (PMID 27434582, 2016). "Hearing manifestations in Wolfram syndrome should be carefully examined because dominant mutations in the WFS1 gene are a common cause of low-frequency sensorineural hearing loss, which is different from Wolfram syndrome." (PMID 26742931, 2016). "Studies of patients with Wolfram syndrome and carriers have identified Wfs1 mutations as causative for MDD." (PMID 26371510, 2015). "Homozygous mutations in the WFS1 gene result in a rare disease—Wolfram syndrome that is characterized by early-onset diabetes mellitus, progressive optic atrophy, diabetes insipidus, and deafness." (PMID 24799886, 2014). "Since the discovery of the association between WFS1 gene and Wolfram syndrome, more than 150 mutations have been identified in WS patients." (PMID 25255707, 2014). "The WFS1 gene, encoding a transmembrane glycoprotein of the endoplasmic reticulum called wolframin, is mutated in Wolfram syndrome, an autosomal recessive disorder defined by the association of diabetes mellitus, optic atrophy, and further organ abnormalities." (PMID 24588001, 2014). "As the mouse model of wolfram syndrome, Wfs1-deficient mice displayed increased anxiety but normal depression level." (PMID 25294992, 2014). "Wolfram syndrome is an early onset genetic disease (1/180,000) featuring diabetes mellitus and optic neuropathy, associated to mutations in the WFS1 gene." (PMID 24823368, 2014). "It is worth emphasizing that mutations in the gene responsible for Wolfram syndrome (WFS1), which is characterized by juvenile diabetes mellitus, optic atrophy and progressive hearing loss, were excluded, as WFS1 is also covered in the NGS deafness panel." (PMID 23813623, 2013). "In humans, a mutation the WFS1 gene encoding the ER transmembrane protein wolframin increases the incidence of DM in Wolfram syndrome patients." (PMID 23762873, 2013).
Wolfram syndrome (continued). "Recessive mutations in WFS1 can lead to Wolfram syndrome (OMIM #222300), which includes diabetes, hearing impairment and psychiatric disease, while heterozygous carriers appear to show no major symptoms associated with diabetes." (PMID 22662265, 2012). "Targeted exome sequencing revealed a homozygous c.1672C > T (p.R558C) missense mutation in exon 8 of WFS1 that has previously been reported in a patient with Wolfram syndrome." (PMID 22226368, 2012). "Caused by mutations in WFS1 on chromosome 4p16.3, Wolfram syndrome is an autosomal recessive neurodegenerative syndrome." (PMID 20069065, 2010). "Homozygous mutations in WFS1 have been linked to the recessively inherited Wolfram syndrome, a syndrome whose features include diabetes insipidus, diabetes mellitus, optic atrophy and sensorineural hearing loss in the high frequencies." (PMID 18518985, 2008). "The fourth and most common locus for LFSNHL is DFNA6/14/38, which results from heterozygous mutations in the Wolfram syndrome type 1 gene (WFS1)." (PMID 18518985, 2008). "Ocular motor, caloric and vestibular ocular reflex testing have not revealed any consistent vestibular dysfunction in patients with Wolfram's syndrome or individuals with heterozygous WFS1 mutations and LFSNHL." (PMID 18518985, 2008). "D4S403 corresponds to a region previously linked to T1D containing the WFS1 gene associated with Wolfram syndrome (MIM #222300), which involves T1D." (PMID 18045462, 2007). "Wolfram syndrome (WS) is the syndrome most closely related to the WFS1 mutation." (PMID 40641032, 2025). "In addition to T2D, genetic loss‐of‐function of WFS1 also results in β cell loss in diabetes of Wolfram Syndrome (WS), which is a prototype of ER stress disorder." (PMID 40192532, 2025). "Wolfram syndrome, caused by WFS1 or CISD2 gene mutations, disrupts ER Ca2+ regulation in neurons." (PMID 39034309, 2024). "Notably, WFS1 is widely known for its mutation, which causes Wolfram syndrome (WS), a rare genetic disorder most frequently characterised by diabetes insipidus, diabetes mellitus, optic atrophy, and deafness." (PMID 39451261, 2024). "Wolfram syndrome is a rare genetic disease caused by mutations in the WFS1 or CISD2 gene." (PMID 39034309, 2024). "This SNP site could serve as a valuable genetic marker for enhancing meat production traits, while also offering potential insights into the underlying mechanisms of Wolfram syndrome caused by WFS1 mutations." (PMID 39451261, 2024). "A 16 week liraglutide administration in an adult with Wolfram syndrome transiently (4 weeks) improved glucose tolerance, while in another individual with an autosomal dominant WFS1 mutation insulin therapy could be discontinued with GLP-1 analogue treatment." (PMID 36995380, 2023). "The causative genes for Wolfram syndrome are WFS1 and WFS2, which encode ER-resident proteins." (PMID 37468098, 2023). "Previous studies of genotype–phenotype correlations for WFS1 mutations in Japanese Wolfram syndrome patients revealed that WFS1 mutation could be subdivided into groups in correlation with clinical severity." (PMID 37440664, 2023). "Activation of the GLP-1 receptor signaling may alleviate insulin insufficiency in Wolfram syndrome and cellular stress caused by WFS1 deficiency." (PMID 37277527, 2023). "Wolfram syndrome (WS; Appendix A includes a list of abbreviations used) is a rare monogenic neurodegenerative disease caused by biallelic mutations in the gene encoding the transmembrane glycoprotein Wolframin (WFS1)." (PMID 37107585, 2023). "Our study provides novel evidence for the beneficial effect of GLP-1R agonists on WFS1-deficient human pancreatic beta cells and neurons, suggesting that these drugs may be considered as a treatment for individuals with Wolfram syndrome." (PMID 36995380, 2023). "Wolfram syndrome is a monogenic disease mainly caused by mutations in the WFS1 gene." (PMID 37440664, 2023).